LEP (leptin)
Diseases named in the same sentence as LEP in open-access papers (continued):
Sharing a sentence is not in itself a finding about the gene and the disease.
metabolic syndrome (continued). "After CPAP treatment of about three months, patients showed a statistically significant decrease in ALT and markers of metabolic syndrome (leptin, CRP, and alpha-tocopherol/total lipid ratio)." (PMID 31540048, 2019). "The synovial tissue and IPFP of OA patients with metabolic syndrome secreted less adiponectin compared to those OA patients with metabolic syndrome, whereas leptin was increased in OA patients with metabolic syndrome." (PMID 31443349, 2019). "Various inflammation markers including NFκβ, TNFα, interleukin-6 (IL-6), monocyte chemoattractant protein (MCP-1), visfatin, resistin, leptin and adiponectin have been identified in the metabolic syndrome pathogenesis." (PMID 31462242, 2019). "Physical activity can improve insulin sensitivity, alleviate plasma dyslipidemia, normalize elevated blood pressure, decrease blood viscosity, promote endothelial nitric oxide production, and improve leptin sensitivity to protect the heart and vessels." (PMID 31093312, 2019). "Leptin increased, whereas soluble leptin receptor and adiponectin decreased with increasing BMI and metabolic syndrome characteristics." (PMID 31453973, 2019). "Some studies have reported that leptin administration can correct many of the metabolic syndromes of liver steatosis." (PMID 30424542, 2018). "The leptin to adiponectin ratio, which has been shown to be a very useful biomarker and predictor of the metabolic syndrome, is increased in both genotypes under HFD but significantly less in ATKlk7−/− mice." (PMID 28932870, 2018). "These focus on a few factors, including a possible confounding role played by serum levels of vitamin D, dyslipidemia, and adipokines such as leptin." (PMID 30618559, 2018). "Insulin and leptin resistance are known to play a role in metabolic syndromes and nonalcoholic fatty liver disease (NAFLD)." (PMID 30055626, 2018). "Leptin represses food intake and increases energy expenditure, and is elevated in women with a metabolic syndrome, likely due to leptin resistance or “hypothalamic leptin insufficiency”." (PMID 29075849, 2018). "Metabolic syndrome and the resulting insulin and leptin resistance and hyperglycemia have pro-inflammatory effects with profound consequences on the BBB." (PMID 30618559, 2018). "With respect to the improved metabolic complications, it is well known that exercise training improves insulin and leptin resistance in conjunction with dyslipidemia by promoting glucose and fatty acid metabolism as well as enhanced mitochondrial biogenesis." (PMID 30343561, 2018). "In MS patients who developed metabolic syndrome, metformin treatment decreases serum leptin and increases adiponectin levels." (PMID 29865151, 2018). "In summary, we report an infant with congenital leptin deficiency due to a novel mutation of the LEP gene, manifesting as severe EOO and dyslipidemia." (PMID 29217499, 2018). "The 4 month-old offspring of HH group had higher body weight, higher levels of plasma triglycerides, leptin, angiotensin I and angiotensin II and abnormal intraperitoneal glucose tolerance test results, which fulfilled the features of metabolic syndrome." (PMID 29618822, 2018). "After controlling for potential confounders, blood CRP, interleukin-6, and leptin were significant predictors of all five individual components of the metabolic syndrome (as both continuous and categorical outcome measures)." (PMID 30190688, 2018). "The relationships between RBP4 levels, the established adipokines (leptin and adiponectin) and the components of MS were examined in 3445 school-aged children recruited in 2004 for the Beijing Child and Adolescent Metabolic Syndrome study." (PMID 29759068, 2018). "In humans, high-caloric diets cause numerous alterations including increased glucose, cholesterol levels and leptin/adiponectin dysregulation leading to cardiovascular disease, metabolic syndrome, and non-alcoholic fatty liver disease." (PMID 29245937, 2017).
metabolic syndrome (continued). "Inflammatory mediators, including adipocyte-derived cytokines such as TNF-α, IL-6, and leptin, are known to induce dyslipidemia." (PMID 28947858, 2017). "Papoutsakis and cols., using the IDF definition of MS in a cohort of 1,138 healthy subjects (normal-weight, overweight, and obese) with a mean age of 11.2 years, demonstrated that leptin is a predictor of the number of metabolic syndrome components present." (PMID 27598976, 2017). "Adipose tissue dysfunction in subjects with nascent metabolic syndromes leads to higher secretion of adipokines, such as IL-1, IL-6, IL-8, leptin, MCP-1, PAI-1, C-reactive protein, and serum amyloid A, by subcutaneous adipose tissue." (PMID 28182687, 2017). "Fasting biochemical evaluation and liver imaging revealed persisting metabolic dyslipidemia, fatty liver, raised plasma testosterone and insulin, and relatively normal adiponectin and leptin." (PMID 29242557, 2017). "A study on metabolic syndrome and leptin has shown a wide variation in leptin levels, even among obese patients (almost seven times between the lowest and highest values in patients with BMI > 40 kg/m2)." (PMID 28226002, 2017). "Even though these markers are well described in literature, some recent findings revealed the possible role of leptin-to-adiponectin ratio in the prediction of cardiometabolic diseases including metabolic syndrome." (PMID 28878827, 2017). "Recent studies have demonstrated in the potential of the leptin-to-adiponectin ratio (LAR) as a novel predictor of cardio-metabolic outcomes including metabolic syndrome." (PMID 28878827, 2017). "In human as well, a randomized controlled trial has shown in patients with metabolic syndrome, that 8 week supplementation with Cur I significantly increased serum adiponectin levels and a reduction in serum leptin concentrations." (PMID 28267745, 2017). "Binary logistic regression analysis revealed that leptin, adiponectin and LAR were significantly associated with metabolic syndrome with respective unadjusted OR of 1.429, 0.468 and 1.502." (PMID 28878827, 2017). "Fasting plasma leptin, triglycerides, cholesterol and phospholipids are elevated, suggesting metabolic syndrome." (PMID 29206867, 2017). "In non-diabetic patients with myotonic dystrophy type 1 (DM1), another multisystemic disease, serum leptin concentration and its relation to metabolic syndrome were evaluated." (PMID 28278160, 2017). "We favored this model instead of leptin-deficiency, because HFD is a more physiologic model of metabolic syndrome and thus more relevant to human disease." (PMID 27884961, 2017). "In particular, consumption of spirulina in a mouse model of metabolic syndrome based on monosodium glutamate injection resulted in decreased serum lipids and leptin concentrations." (PMID 26779620, 2016). "Leptin resistance is a possible player in the roadmap to the metabolic syndrome and type 2 diabetes, and it has been suggested that leptin can protect against lipotoxicity." (PMID 27216013, 2016). "Improvements in the lipid profile seen in patients using metreleptin (an analog of human leptin) confirm the important role of leptin in the treatment of dyslipidemia." (PMID 26985241, 2016). "It has been found that rice bran derivatives reduce plasma and liver lipids, whereas protein hydrolysates from rice bran improve insulin and leptin sensitivity in high-fat diet-induced metabolic syndrome in hamsters." (PMID 27821167, 2016). "In the case of level of leptin relationship to body fat and the prevalence of metabolic syndrome it is quite the opposite." (PMID 27212946, 2016). "Long-term leptin administration has a sustained effect to improve dyslipidemia in hypoleptinemic group of lipodystrophic patients." (PMID 27307101, 2016). "Two recent studies proved that FSH was a biomarker to assess the probability of metabolic syndrome better than C-reactive protein, leptin or SHBG in postmenopausal women." (PMID 25959422, 2016).
metabolic syndrome (continued). "Chronic elevated cortisol levels and leptin resistance can still explain the lower secretion of BDNF found in morbidly obese children and children with metabolic syndrome, and they are associated with deficits in cognition and synaptic plasticity." (PMID 27907172, 2016). "To analyze influence of systemic inflammatory response to metabolic syndrome, we inoculated an attenuated vaccine strain of Mycobacterium bovis Bacillus Calmette–Guérin (BCG) into leptin-deficient ob/ob mice." (PMID 26039731, 2015). "In yet another clinical study, L : A ratio has been demonstrated as a useful biomarker for the prevalence of metabolic syndrome, in comparison with either leptin or adiponectin levels on their own." (PMID 25650072, 2015). "The aim of this study was to determine the levels of leptin (Lep) and adiponectin (AdipoQ) in patients with gout and its relationship with joint inflammatory data and/or with metabolic syndrome (MetS) variables, during 1 year follow-up." (PMID 26131838, 2015). "Mammals with a metabolic syndrome phenotype often have altered levels of leptin in the blood stream." (PMID 25856311, 2015). "Treatment with BC (100 or 300 mg/kg/day for 8 weeks) significantly suppressed increased liver weight, epididymal fat weight, C-reactive protein (CRP), total bilirubin, leptin, and insulin in rats with induced metabolic syndrome." (PMID 26504474, 2015). "One interesting clue is the stronger association of Leaf 5 with clinical markers of dyslipidemia (VLDL, triglyderides) and Leaf 8 with glucose homeostasis (leptin)." (PMID 25643280, 2015). "The metabolic syndrome was assessed by measuring the body weight gain, the glucose sensitivity, and the levels of insulin, triglyceride, leptin, and aspartate aminotransferase transaminase (AST) and alanine aminotransferase (ALT)." (PMID 25874022, 2015). "One by-product of these activation-dependent cytokines is the development of metabolic syndrome phenotypes characterized by weight gain and/or leptin resistance." (PMID 25856311, 2015). "Significant findings including the correlation of triglyceride changes with leptin changes confirm the effectiveness of hypoxic training on the modulation of dyslipidemia in MetS." (PMID 25885799, 2015). "Abdominal obesity is a key feature of metabolic syndrome as visceral fat is responsible for the secretion of various adipocytokines such as leptin, interleukin-6 and adiponectin." (PMID 26593941, 2015). "Some reported that leptin administration will correct many of the metabolic syndromes including hepatic steatosis." (PMID 24822223, 2014). "This study was aimed to determine adiponectin and leptin levels in saliva and plasma from patients with metabolic syndrome, and evaluate any correlation of these levels with MS." (PMID 24528653, 2014). "In this study, we present a whole-genome fully factorial examination of the transcriptional consequences of the interactions between maternal diet, leptin treatment, postweaning diet and metabolic syndrome in a rat model of developmental programming." (PMID 24447410, 2014). "In line, recently an important role of AMPK in cardiac remodeling was demonstrated in leptin and LDL-receptor deficient mice, another model of the metabolic syndrome." (PMID 24416343, 2014). "Previous studies have linked decreased levels of leptin and adiponectin to HIV infection, particularly in the context of HIV-associated lipodystrophy, a syndrome characterized by fat redistribution, dyslipidemia, and metabolic syndrome." (PMID 25050734, 2014). "Serum leptin levels were significantly higher in the metabolic-syndrome group than the control group (p < 0.01), but the BDNF difference between them was not significant." (PMID 24444121, 2014). "In return, we found a statistically significant decrease in leptin levels after exercise testing in all patients with metabolic syndrome." (PMID 24616817, 2014).
metabolic syndrome (continued). "The effect of selective leptin resistance on disease progression and the metabolic syndrome is complicated." (PMID 24750587, 2014). "Pre-specified secondary outcomes were changes in body weight, HOMA-IR, metabolic syndrome (MS) measures, leptin, and adiponectin." (PMID 25259787, 2014). "So high leptin levels are involved not only in the appearance and progression of atherosclerosis but also in the development of arterial hypertension and metabolic syndrome." (PMID 24616817, 2014). "There is growing evidence that women with a previous history of PE tend to develop metabolic syndromes several years later, including insulin resistance, dyslipidemia, higher blood pressure, body mass index (BMI), and leptin levels." (PMID 25050336, 2014). "Among the components of metabolic syndrome, abdominal obesity is only weakly correlated with serum leptin levels." (PMID 24825928, 2014). "Hyperleptinemia is usually associated with a progressive increase in body weight and the development of metabolic syndrome, leading to global or selective leptin resistance." (PMID 24825928, 2014). "Low-grade systemic inflammation, elevated leptin concentration and low adiponectin level are described in very young obese children, correlating with a range of variables of metabolic syndrome." (PMID 24571954, 2014). "Plasma leptin levels in patients with metabolic syndrome were 9.42 ± 11.08 ng/mL before performing the exercise testing." (PMID 24616817, 2014). "Mice made obese on the 60% diet displayed elevated glucose, insulin, HOMAIR scores, and leptin and lower concentrations of adiponectin, which together are characteristics of metabolic syndrome." (PMID 25072025, 2014). "The strength of this study is in its study design which allows the prospective examination between the serum leptin and the metabolic syndrome." (PMID 24455217, 2013). "Ethnic comparative studies of adults have shown higher levels of leptin and lower levels of adiponectin in the ethnic populations with the highest prevalence of metabolic syndrome, even when degree of adiposity and other confounders is accounted for." (PMID 23940841, 2013). "Hypoxic preconditioning was induced in C57Bl6-mice (WT), leptin deficient ob/ob (model for type II diabetes) and double knock-out (DKO) mice with combined leptin and LDL-receptor deficiency (model for metabolic syndrome)." (PMID 23432808, 2013). "In multivariate analysis, men in quintile 5 of serum leptin were at higher odds of developing metabolic syndrome at year 6 as compared to those in quintile 1 after adjusting for potential confounders." (PMID 24455217, 2013). "Leptin was associated with HOMA-IR (r = 0.369; P <0.001), Metabolic syndrome criteria number (r = 0.388; P <0.001), waist circumference (r = 0.488; P <0.001), and TG (r = 0.264; P <0.001)." (PMID 24245495, 2013). "We propose that components of the metabolic syndrome and the insulin-leptin-adiponectin axis play a pivotal role in the pathogenesis and progression of TNBC." (PMID 22295251, 2012). "The results found in the present study indicate that adult females of the Iberian pig, a swine breed with leptin resistance, can develop the prodrome of metabolic syndrome and type 2 diabetes when allowed to freely eat a diet enriched with saturated fat." (PMID 22629144, 2012). "Our clinical observation showed that in patients with newly diagnosed metabolic syndrome the level of leptin dropped significantly with berberine treatment after 3 months." (PMID 22474499, 2012). "The associations between leptin and CRP levels with metabolic syndrome score, which is determined as the number of metabolic syndrome components described by the ATP III criteria, was next determined." (PMID 22533665, 2012). "After adjusting for age, leptin levels significantly increased with increasing metabolic syndrome score in both male and female subjects (P < 0.05)." (PMID 22533665, 2012).
metabolic syndrome (continued). "Both leptin and CRP levels were associated with cardiovascular risk factors as well as metabolic syndrome score in both men and women although gender-specific differences were observed." (PMID 22533665, 2012). "In this study, further associations between leptin and CRP levels and metabolic syndrome score were detected in both male and female participants." (PMID 22533665, 2012). "After 3 months of treatment, metabolic syndrome patients showed decrease in their BMI (31.5 ± 3.6 versus 27.4 ± 2.4 kg/m2) and leptin levels (8.01 versus 5.12 μg/L), as well as leptin/adiponectin ratio and HOMA-IR." (PMID 22474499, 2012). "This is the first study to explore the possible association and interaction between leptin and CRP levels with risk factors for cardiovascular disease and metabolic syndrome in a Taiwanese population." (PMID 22533665, 2012). "The present study is one of the few studies to analyze the relationship between leptin levels and metabolic syndrome in an Asian population." (PMID 21526991, 2011). "Although few, population studies describing the relationship between leptin levels and metabolic syndrome have been reported." (PMID 21526991, 2011). "In conclusion, serum leptin levels are correlated with CVD risk and metabolic syndrome in Taiwanese adults." (PMID 21526991, 2011). "Little is known regarding the associations between high-molecular-weight (HMW-) adiponectin, leptin and soluble leptin receptor (sOB-R) and metabolic syndrome (MetS) in Chinese." (PMID 21347230, 2011). "Resistance to Leptin, an important adipokine has been suggested as an alternative concept to explain the metabolic syndrome." (PMID 21991518, 2011). "WHR, fasting glucose and plasma leptin levels, which suggested TNFA allele would increase the risk of metabolic syndrome." (PMID 21494616, 2011). "In overweight or obese patients with untreated dyslipidemia, rimonabant decreased leptin levels to a greater extent than in patients with diabetes (23%) and significantly increased adiponectin levels by 37%." (PMID 21276223, 2011). "In men, compared to the lowest leptin quartile, the odds ratio (OR) and 95% confidence intervals (95% CI) for metabolic syndrome after adjusting for age were 3.28 (2.06 - 5.20) in Q2, 5.12 (3.13 - 8.37) in Q3 and 6.14 (3.70 - 10.19) in Q4 (p < 0.001)." (PMID 21526991, 2011). "The relationship between leptin levels and metabolic syndrome was further explored using ROC analysis to determine the predictive value of leptin levels for metabolic syndrome in men and women." (PMID 21526991, 2011). "Leptin is associated with cardiovascular disease (CVD); however, few studies have assessed its relationship with metabolic syndrome, especially in an Asian population." (PMID 21526991, 2011). "Correlation between leptin levels and metabolic syndrome was observed in both male and female participants." (PMID 21526991, 2011). "Leptin levels were also predictive of metabolic syndrome in both sexes, which is similar to other studies." (PMID 21526991, 2011). "For example, in adult males participating in the Olivetti Prospective Heart Study, leptin levels were predictor of developing metabolic syndrome at 8-year follow-up." (PMID 21526991, 2011). "In the present study, increased odds of metabolic syndrome with increasing leptin levels were observed in both sexes upon adjusting for age and tobacco usage." (PMID 21526991, 2011). "According to our knowledge, this is the first study that examined the effect of soy consumption in the form of soy nut and soy protein on serum leptin levels in postmenopausal women with metabolic syndrome." (PMID 21526104, 2010). "Recently, leptin therapy has been reported to correct hyperglycemia, dyslipidemia, and hepatic steatosis both in congenital and acquired forms of lipodystrophy." (PMID 21274335, 2010). "Patients in the current study had all five components of metabolic syndrome, and the leptin level was elevated in these patients." (PMID 21526104, 2010).